MUC5AC (mucin 5AC, oligomeric mucus/gel-forming)
Diseases named in the same sentence as MUC5AC in open-access papers (continued):
Sharing a sentence is not in itself a finding about the gene and the disease.
lung carcinoma (35 papers, 2014 to 2025). "The mechanisms underlying the role of MUC5AC in lung cancer are complex and multifaceted, involving tumor promotion, brain metastasis, cell migration, and chemoresistance." (PMID 40655139, 2025). "Meanwhile, we found that high level of MUC5AC (P = 0.039), low expression of circRABL2B (P = 0.016) were associated with poor survival of lung cancer patients." (PMID 37324942, 2023). "MUC5AC is overexpressed in lung cancer tissues and associated with poor survival of lung cancer patients." (PMID 37324942, 2023). "It has been shown that the well-known modifier of CF lung disease, Mucin 4 (MUC4) and Mucin 5AC (MUC5AC) are associated with lung cancer risk and prognosis, respectively." (PMID 34415821, 2022). "PacBio targeted sequencing has also been used to resolve the genomic gap in MUC5AC, which encodes a large, secreted mucin that is important in cystic fibrosis, lung cancer, and respiratory diseases." (PMID 26542840, 2015). "MUC5AC has been implicated in lung cancer cell metastasis and growth, and its knockdown has led to decreased migration of cancer cells and reduced tumor-promoting signaling pathways, particularly via integrin-mediated pathways which are essential for cancer cell adhesion and motility." (PMID 40655139, 2025). "MUC5AC’s presence in lung cancer is predictive of tumor aggressiveness and adverse prognosis, correlating directly with malignant features such as lymphatic dissemination, tumor size, and radiographic indicators like lobed and burr signs." (PMID 40655139, 2025). "S100A12, as well as S100A8 and S100A9, was shown to activate TLR4 and RAGE in normal bronchial epithelial cells and lung carcinoma cells in vitro to produce MUC5AC, a predominant protein in mucin." (PMID 41164170, 2025). "To determine the role of ST6GalNAc-I and MUC5AC in non–small cell lung cancer development and metastasis, we performed intratracheal lung orthotopic experiments using A549 ST6GalNAc-I–KO and MUC5AC-KD and respective control cells." (PMID 40371640, 2025). "The circular RNA (circRNA) circRABL2B negatively correlates with MUC5AC in lung cancer, and patients with low circRABL2B and high MUC5AC exhibit poorer survival." (PMID 38255791, 2024). "They found that lowering MUC5AC in lung cancer cells greatly reduced their movement to the brain in mice." (PMID 38825648, 2024). "Next, we detected secreted MUC5AC in culture supernatants from lung cancer cells and lung tumoroids by immunoblotting." (PMID 38632190, 2024). "The results showed that MUC5AC expression was positively correlated with the resistance of lung cancer cells to erlotinib (r = 0.459, P = 0.018)." (PMID 37324942, 2023). "In the current study, we report that circRABL2B is negatively correlated with MUC5AC and downregulated in lung cancer, which indicates poor survival." (PMID 37324942, 2023). "The patients who expressed both low circRABL2B and high MUC5AC displayed the worst survival rate, suggesting circRABL2B and MUC5AC to be bi-target for treatment of lung cancer." (PMID 37324942, 2023). "Instead, here we found circRABL2B, which decreases MUC5AC expression, acts to decrease the proportion of SP cells in lung cancer." (PMID 37324942, 2023).
lung carcinoma (continued). "Our results demonstrate that the mucus found in lung cancer (mucinous adenocarcinoma) has elevated levels of MUC5AC as compared to UIP mucus." (PMID 37005656, 2023). "Mechanically, circRABL2B retards lung cancer progression by synergizing YBX1 to degrade MUC5AC mRNA and impoverish cancer cell stemness." (PMID 37324942, 2023). "FOXA3 and SPDEF induce MUC5AC and MUC5B, while HNF4A induces MUC3 in human lung cancer cells harboring a KRAS mutation." (PMID 36860703, 2022). "We previously found that MUC5AC production was reduced in NCI–H292 human lung cancer epithelial cells and human primary asthmatic lung cells cultured with Col4." (PMID 34504957, 2021). "MUC5AC interacts with integrin β4 and enhances the migration of lung cancer cells through focal adhesion kinase signaling." (PMID 34504957, 2021). "The expression data also showed 1.7-fold up regulation of MUC5AC in radiation resistant cells, and functionally it has been linked to focal adhesion kinase (FAK) phosphorylation, and lung cancer proliferation, and KRAS mutated aggressive lung cancer." (PMID 34762666, 2021). "Further, we found up-regulation of a tumor-promoting mucin gene Muc5ac recently shown to be necessary for Kras-mutant lung cancer initiation." (PMID 31001473, 2019). "MUC5AC mediates metastasis of cancer cells by interacting with integrin β4–FAK signaling in lung cancer cells." (PMID 30420637, 2018). "Previously, our ChIP‐seq analyses determined that NKX2‐1 and FOXA3 bound to the locus of MUC5AC in A549 lung carcinoma cells and BEAS‐2B transformed bronchial epithelial cells, suggesting that the expression of MUC5AC is directly regulated by NKX2‐1 and FOXA3." (PMID 28255028, 2017). "With respect to the secreted, gel forming mucins, NAC treatment was shown to hamper the expression of MUC5AC in lung carcinoma cells." (PMID 26436698, 2015). "In lung cancer, particularly LUAD, MUC5AC expression is significantly upregulated and correlates with tumor invasiveness, lympho-vascular invasion, tumor heterogeneity, and poor prognosis (Human lung cancer cohort study)." (PMID 40655139, 2025). "Knock-down of MUC5AC significantly inhibited cell proliferation and migration of lung cancer cells." (PMID 37324942, 2023). "Furthermore, siRNAs-mediated knockdown of EIF4a3 significantly decreased circRABL2B expression and increased MUC5AC level in lung cancer cells." (PMID 37324942, 2023). "To delineate whether MUC5AC is an essential target of circRABL2B on affecting malignant phenotypes of lung cancer, we knocked down MUC5AC by siRNAs in circRABL2B knock-down cells, where MUC5AC expression was increased." (PMID 37324942, 2023). "Besides, patients with both high MUC5AC and low circRABL2B exerted the worst survival after adjustment for age, sex, smoking status, family history of lung cancer, and clinical stage (HR=2.00; 95%CI=1.12-3.57)." (PMID 37324942, 2023). "Knock-down of MUC5AC also inhibited lung cancer growth and migration." (PMID 37324942, 2023). "High-throughput sequencing of 141 lung cancer patient samples revealed a significant inverse correlation between circRABL2B and MUC5AC expression, with patients exhibiting low circRABL2B and high MUC5AC levels showing the worst survival outcomes (HR = 2.00; 95% CI = 1.12–3.57)." (PMID 40655139, 2025). "Additionally, MUC5AC interacts with PRRC1 to enhance tumor glycosylation, which in turn boosts angiogenesis and metastatic potential.Overexpression of MUC5AC has been associated with cisplatin resistance in lung cancer cells." (PMID 40655139, 2025). "Furthermore, the pathological effects of MUC5AC in lung cancer go beyond immune modulation." (PMID 40655139, 2025).
lung carcinoma (continued). "This suggests that focusing on MUC5AC could help stop lung cancer from moving to the brain." (PMID 38825648, 2024). "Thus, we suggest that Der p 2 may also promote motility of lung carcinoma cells via upregulation of MUC5AC." (PMID 28076322, 2017). "The interaction between MUC5AC and integrin β4 activates downstream signaling pathways by recruiting phosphorylated FAK (Y397), leading to lung cancer cell migration." (PMID 40655139, 2025). "In support of this finding, we observed reduced ST6GalNAc-I, MUC5AC, and VCAN-V1 in ST6GalNAc-I/MUC5AC–depleted lung tumor tissues, suggesting that the ST6GalNAc-I/MUC5AC axis is required for lung cancer liver metastasis." (PMID 40371640, 2025). "The research, led by Sanjib Chaudhary and team, discovered that MUC5AC works with another protein, ANXA2, to help lung cancer cells move to the brain." (PMID 38825648, 2024). "In this study, the effects of integrin β1 subunit on MUC5AC and MUC5B production were examined in NCI–H292 human lung cancer epithelial cells." (PMID 34504957, 2021). "MUC5AC interacts with integrin β4 recruit phosphorylation of FAK (Y397) activated downstream signaling pathways, leading to lung cancer cell migration." (PMID 32807223, 2020). "MUC5AC was proved to interact with integrin β4 that mediates phosphorylation of FAK at Y397, resulting in lung cancer migration." (PMID 28938681, 2017). "Interestingly, limited secreted MUC5AC was detected in all types of lung cancer cells used, including NCI-H2122 cells, in which MUC5AC mRNA expression was detected by q-PCR." (PMID 38632190, 2024). "Consistently, TCGA data demonstrated a negative correlation between expressions of EIF4a3 and MUC5AC in lung cancer." (PMID 37324942, 2023). "In the cohort of 141 lung cancer patients, we confirmed the negative correlation of expressions between circRABL2B and MUC5AC (r = -0.193, P = 0.022)." (PMID 37324942, 2023). "In ALK + lung cancer, there is a higher incidence of MUC1 and MUC5AC cytoplasmic expression, which, combined with a paucity of MUC2 and MUC6 expression, could lead to the biological aggressiveness of ALK + cancer." (PMID 36059804, 2022). "Interestingly, the data have shown several fold upregulation of DNA repair genes like RAD51b, RAD 18 and SOX2 cancer stem cell markers, MUC5AC and TGFBR2 in radiation resistant and caveolin-1, overexpressed A549 lung cancer cells." (PMID 34762666, 2021). "As expected, tumor tissues from the colon and pancreas expressed tumor-specific MUC5AC while the normal colon/pancreas and lung cancer tissues did not." (PMID 34205412, 2021). "Involvement of highly significant DEGs including SLCO1A2, OLFM4, RTKN2, CYP1A1, and MUC5AC plays a key role in rheumatoid arthritis development.Highly significant DEGs including OLFM4, RTKN2, CYP1A1, MUC5AC, CYP2A6, PCK1, and PITX1 have been reported to encourage the development of lung cancer." (PMID 38137330, 2023). "Interestingly, lung cancer tissues stained with 45M1 Mab reacts to native MUC5AC but not to NPC-1C Mab." (PMID 34205412, 2021). "However, it is unknown whether SPDEF directly binds to the loci of MUC5AC and/or MUC5B in lung carcinoma cells." (PMID 28255028, 2017). "In addition, the circSULF2 is up-regulated in lung cancer tissues in comparison with adjacent normal lung tissues, and in lung cancer cell lines when compared to normal lung cell lines, and its expression is positively correlated with MUC5B (r = 0.266, P = 0.001) but not MUC5AC." (PMID 37324942, 2023).
Airway obstruction (34 papers, 2011 to 2026). Obstruction of conducting airways of the lung. "NE regulates expression of the MUC5AC gene, which encodes the gel-forming mucin of the respiratory tract, through an ROS-dependent mechanism associated with airway obstruction and disease severity." (PMID 34681202, 2021). "In addition, IL-17A can act with IL-6 to induce MUC5AC, and PM excessively regulates the expression of MUC5AC, causing excessive mucus production in the airways and exacerbating airway obstruction." (PMID 35837279, 2022). "MUC5AC increases mucus production, and increased mucus production followed by stimulated secretion, which may cause histological changes such as mucus plugging and airway obstruction." (PMID 35214853, 2022). "By reducing MUC5AC expression, this gene therapy has the potential to decrease mucus viscosity, improve mucus clearance, and interrupt the cycle of airway obstruction, infection, and inflammation responsible for progressive lung damage." (PMID 41446468, 2025). "Our results further demonstrate that EPO-BM-MSCs suppress the expression of mucin markers (MUC5AC and MUC5B) in asthmatic lungs, which is critical for alleviating airway obstruction—a hallmark of severe asthma." (PMID 41023810, 2025). "In many obstructive pulmonary diseases, excessive secretion, especially Muc5ac, and imbalanced water-to-mucin ratios can lead to increased mucus viscosity and airway obstruction." (PMID 37924136, 2023). "Muc5AC and Muc5B gene expression in obstructive lung diseases have been dissected in numerous studies, and notably in cigarette smoke exposure models." (PMID 35269434, 2022). "Mucin 5AC (MUC5AC), an integral component of mucus in the airway, is significantly upregulated in the pathogenesis of allergic asthma, and its increase is related to airway obstruction." (PMID 33919784, 2021). "M2 macrophage-induced IL-8 causes the production of neutrophil-elastase, which, in turn, promotes MUC5AC expression, leading to mucus hypersecretion and airway obstruction." (PMID 33919784, 2021). "Additionally, IL-17A and IL-17 F stimulate airway epithelial and smooth muscle cells to produce mucins (MUC5B and MUC5AC), enhancing mucus hypersecretion and contributing to airway obstruction." (PMID 39850030, 2024). "However, it does show that severe RSV disease is associated with physical changes to the mucus, as increases in a gel-forming mucin MUC5AC likely results in increased mucus viscosity and airway obstruction." (PMID 35406717, 2022). "Increased secretion of MUC5AC in airway epithelial cells exhibits a protective role against influenza-induced lung injury but does not cause airway obstruction." (PMID 34149803, 2021). "However, muc5AC knockout mice had a 74% reduction in airway obstruction when challenged with antigens to mimic allergic asthma." (PMID 31752894, 2019). "In addition, MUC5AC expression in COPD patients correlated negatively with airway obstruction in terms of FEV1 and FEV1/FVC ratio (Fig. E3,A,B) (while β-tubulin IV in current and former smokers negatively correlated with pack years (Fig. E3,C)." (PMID 31784664, 2019). "IL-13 has been reported to play an indispensable role in mounting bronchial hyperreactivity (BHR) and goblet cell hyperplasia, caused by elevated expression of the mucin proteins MUC5AC and MUC5B, leading ultimately to mucus overproduction and airway obstruction." (PMID 26346739, 2015). "MUC5AC, the major glycoprotein component of mucus encoded by the conserved muc5ac gene, is expressed in airway epithelial cells and mediates IL-17A-induced mucus cell hyperplasia and mucus production via STAT3 signaling, thereby contributing to airway obstruction and inflammation." (PMID 41304567, 2025). "Finally, EGFR inhibition may alleviate mucus hypersecretion by suppressing mechanical-stress-induced ERK/MUC5AC signaling, offering a targeted strategy to reduce airway obstruction." (PMID 40995116, 2025).
Airway obstruction (continued). "In agreement with the previous studies, CSM exposure induced MUC5AC overexpression with further upregulation of MUC5AC expression after SARS-CoV-2 infection, suggesting that SARS-CoV-2 might aggravate mucus hypersecretion to cause further airway obstruction in smokers and COPD patients." (PMID 37041586, 2023). "Among these, IL-1β can trigger PTGS2 to induce MUC5AC mucin expression through ERK or p38 MAPK, exacerbating airway obstruction, whereas TNF-α may induce PTGS2 to produce prostaglandin E2 (PGE2) and other substances, exacerbating airway inflammation." (PMID 41557720, 2026). "The increase of Muc5ac secretion in bronchiolar epithelium without changes in motile cilia recovery suggests an accumulation of mucus in the airway, leading to the airway obstruction described in COPD." (PMID 36230899, 2022). "The observed correlation between MUC5AC concentrations and peak expiratory flow rate (PEFR) decline may be explained by the likelihood that greater mucus production contributes directly to airway obstruction during exacerbations." (PMID 35239513, 2022). "Additionally, S100A12 produces secreted mucin 5AC (MUC5AC) from airway epithelial cells, which is related to an increased intracellular mucin production that could predispose e-cigarette users to airway obstruction similar to chronic obstructive pulmonary disease patients." (PMID 33924379, 2021). "The alterations in mucin composition we observed, namely increased MUC5AC and low-charge MUC5B, may contribute to a pathologic mucus gel with altered mucus biophysical properties leading to airway obstruction." (PMID 28716644, 2017). "While mucins MUC-5AC and MUC-5B are the principal secreted mucins found in the airways of healthy individuals, their levels are substantially elevated in patients with moderate COPD compared to both non-smokers and smokers without airway obstruction." (PMID 40604933, 2025). "Importantly, in a study of COPD, the relative amounts of MUC5AC and MUC5B were shown to differ in smokers with and without airway obstruction, suggesting that the mucin composition of mucus is a major factor for efficient mucus transport." (PMID 21602926, 2011).